USP5 (ubiquitin specific peptidase 5)
Diseases named in the same sentence as USP5 in open-access papers (continued):
Sharing a sentence is not in itself a finding about the gene and the disease.
lung cancer (continued). "Finally, the investigations in vivo are executed using the mice subcutaneous tumor model to identify the effect of USP5 in promoting lung cancer development." (PMID 37060095, 2023). "Overall, our findings suggest that pharmacologically targeting USP5 may represent a potential strategy for targeting lung CSCs and reducing the number of deaths from lung cancer metastasis." (PMID 37726816, 2023). "To further investigate the potential oncogenic roles of USP5-PD-L1 axis on lung cancer progression in vivo, we established mouse Lewis lung carcinoma cells (LLC) stably expressing control (Ctrl) or USP5 shRNA, in which the USP5 protein and mRNA were successfully knockdown." (PMID 34741014, 2021). "In addition, this connection could also be observed in clinical specimens, which showed that USP5 was positively correlated with SNAI2 expression in two independent lung cancer datasets." (PMID 37726816, 2023). "First, we found that USP5 silencing caused a reduction in β-catenin expression at the protein level but not at the mRNA level in CL1-5 cells In addition, the similar results could be observed in H23, H522, and H1299 lung cancer cells." (PMID 37726816, 2023). "Next, we also tested whether WP1130 treatment inhibits USP5-mediated functions in lung cancer." (PMID 37726816, 2023). "To explore this, we next investigated whether USP5 can promote stemness properties in lung cancer." (PMID 37726816, 2023). "Therefore, this evidence shows that targeting USP5 using the small compound WP1130 may have therapeutic potential for lung cancer treatment." (PMID 37726816, 2023). "Moreover, lung cancer patients with either high USP5 or Beclin 1 protein levels had a worse OS." (PMID 36528652, 2022). "Altogether, these findings suggest that USP5 induces Slug expression and promotes EMT in lung cancer." (PMID 37726816, 2023). "NSCLC studies have shown that high expression levels of USP5 and USP7 in lung cancer tissue promote lung cancer cell proliferation by stabilizing beta‐catenin." (PMID 33619866, 2021). "In addition, USP5 overexpression upregulated PARP1, while its knockdown downregulated PARP1in lung cancer cells." (PMID 37060095, 2023). "Together, USP5 could promote the progression of lung cancer cells by mTOR signaling pathway and interacting with PARP1, indicating that USP5 may become a new target for lung cancer treatment." (PMID 37060095, 2023). "However, the relationship between USP5 and EMT remained largely unknown in lung cancer." (PMID 37726816, 2023). "The lung cancer cells treated with USP5 could not effectively disregard the effects of PARP1 knockdown on their progression, inferring that the USP5 might function effectively combined with PARP1." (PMID 37060095, 2023).
breast cancer (8 papers, 2021 to 2025). A primary or metastatic malignant neoplasm involving the breast. "Recent studies have demonstrated that USP5 expression is significantly upregulated in breast cancer cells, where it promotes cell proliferation and migration, potentially through the stabilization of HIF-2α." (PMID 41213937, 2025). "In summary, we can preliminarily confirm that DEPDC1B mediates the ubiquitin level of β-catenin by binding with USP5 and β-catenin in breast cancer cells." (PMID 37642235, 2023). "Immunofluorescence results showed that DEPDC1B, USP5, and β-catenin were colocalized in breast cancer cells." (PMID 37642235, 2023). "Coimmunoprecipitation (Co-IP) results showed that there was an interaction relationship between DEPDC1B and β-catenin and between DEPDC1B and USP5 in breast cancer cells." (PMID 37642235, 2023). "USP5 is a common cysteine deubiquitin enzyme that is highly expressed in many cancers, including breast cancer." (PMID 37642235, 2023). "Similarly, USP5 is identified as a novel deubiquitinase for HIF2α in breast cancer, interacting with and stabilizing HIF2α by preventing its ubiquitin–proteasome degradation." (PMID 40750708, 2025). "It has also been reported that high USP5 expression in breast cancer leads to poor clinical prognosis, and its molecular mechanism is related to the promotion of breast cancer cell proliferation, migration, and invasion by stabilizing the HIF2α protein through deubiquitination activity." (PMID 37642235, 2023). "Furthermore, we also revealed a novel mechanism in DEPDC1B-mediated USP5 deubiquitination of β-catenin, which led to the activation of the wnt/β-catenin signaling pathway and ultimately promoted breast cancer cell metastasis." (PMID 37642235, 2023). "Therefore, it can be inferred that USP5 influences breast cancer progression by targeting either the HIF protein or the PFKP protein, which in turn may directly or indirectly impact the function of PFKP." (PMID 38217030, 2024). "Therefore, we hypothesized that in breast cancer cells DEPDC1B inhibits the ubiquitination of β-catenin by binding to USP5 and β-catenin." (PMID 37642235, 2023). "USP5 has been shown to interact with and deubiquitinate HIF-2α in breast cancer models, and its protein level is positively correlated with HIF-2α protein levels in human breast cancer tissues." (PMID 39584532, 2024). "Finally, we found that in breast cancer cells DEPDC1B mediates the deubiquitination of β-catenin by USP5, stabilizes the β-catenin protein level, promotes nuclear translocation, activates the wnt/β-catenin signaling pathway, and ultimately promotes the transfer of breast cancer cells." (PMID 37642235, 2023). "In addition, we also proved that DEPDC1B, USP5, and β-catenin colocalize in breast cancer cells and that DEPDC1B promotes the deubiquitination of β-catenin by USP5." (PMID 37642235, 2023).
bladder cancer (6 papers, 2021 to 2025). "USP5 protein levels are significantly elevated and positively associated with Twist1 levels in clinical bladder cancer samples." (PMID 41228251, 2025). "Our results demonstrated that USP5 deficiency significantly inhibits the proliferation and colony formation of T24 bladder cancer cells." (PMID 40136465, 2025). "Clustered regularly interspaced short palindromic repeats (CRISPR)/Cas9 technique was used to construct bladder cancer T24 USP5-deficient cells (USP5−/−)." (PMID 40136465, 2025). "In this study, we found that USP5 deficiency inhibits the proliferation of T24 bladder cancer cells." (PMID 40136465, 2025). "To investigate the molecular mechanism of USP5 in bladder cancer, we performed RNA-seq analysis using USP5-deficient and WT T24 cells." (PMID 38229092, 2024). "To determine the function of USP5 in bladder cancer, we constructed USP5-overexpressing and USP5-deficient cancer cell lines." (PMID 38229092, 2024). "In conclusion, our experimental results showed that USP5 is associated with poor prognosis in bladder cancer." (PMID 38229092, 2024). "Thus, USP5 deficiency promotes ferroptosis in bladder cancer cells." (PMID 40136465, 2025). "Future research should focus on developing USP5 inhibitors and exploring their efficacy in preclinical and clinical settings, with the ultimate goal of improving outcomes for patients with bladder cancer." (PMID 40136465, 2025). "In conclusion, our study demonstrated that USP5 plays a critical role in bladder cancer progression by promoting cell proliferation and inhibiting ferroptosis through the stabilization of GPX4." (PMID 40136465, 2025). "Our findings further support the notion that USP5 plays a crucial role in bladder cancer progression by promoting cell proliferation and tumor formation." (PMID 40136465, 2025). "While our study provides valuable insights into the role of USP5 in bladder cancer and ferroptosis, several limitations should be addressed in future research." (PMID 40136465, 2025). "Our previous study demonstrated that USP5 is overexpressed in bladder cancer and promotes cell proliferation, migration, and tumor formation." (PMID 40136465, 2025). "In this study, we focused on investigating the molecular mechanism of ferroptosis induced by USP5 in bladder cancer." (PMID 40136465, 2025). "We found that the Fe2+, MDA, and ROS contents were increased in bladder cancer cells when USP5 was depleted." (PMID 40136465, 2025). "The results revealed a significant positive correlation between USP5 and GPX4 RNA levels in bladder tissue on the basis of the GTEx data and a positive association between USP5 and GPX4 RNA levels in bladder cancer tissue on the basis of the TGCA data." (PMID 40136465, 2025). "Our study focused on the role of USP5 in bladder cancer and its mechanism, aiming to provide new ideas and targets for the treatment of bladder cancer." (PMID 40136465, 2025). "Our experimental results revealed that USP5 deletion caused a more significant increase in the content of the ferroptosis markers Fe2+, MDA and ROS in bladder cancer cells after the addition of erastin." (PMID 40136465, 2025). "The results revealed a positive association between USP5 and GPX4 RNA levels in bladder cancer tissue." (PMID 40136465, 2025). "The role of USP5 in bladder cancer was evaluated using T24 wild-type cells (WT) and USP5 knockout (USP5−/−) by CCK8 and colony formation assays." (PMID 40136465, 2025). "Together, these experimental observations indicate that USP5 plays a crucial role in maintaining the proliferative and survival capacity of T24 bladder cancer cells." (PMID 40136465, 2025). "Then, we performed overall survival analysis with data from GEPIA, and the results suggested that bladder cancer patients with high USP5 expression had poorer survival outcomes than those with low USP5 expression." (PMID 38229092, 2024).
bladder cancer (continued). "Genetic ablation of USP5 markedly inhibited bladder cancer cell proliferation, viability, and migration both in vitro and in vivo." (PMID 38229092, 2024). "We found that USP5 was overexpressed in bladder cancer samples and that patients with high USP5 expression had an unfavourable prognosis." (PMID 38229092, 2024). "The results of IHC staining experiments with a tissue microarray were revealed that USP5 was highly expressed in bladder cancer compared with normal tissue." (PMID 38229092, 2024). "To verify USP5 expression in bladder cancer, we analysed USP5 protein levels in bladder cancer tissues and adjacent bladder tissues from patients using immunohistochemistry (IHC)." (PMID 38229092, 2024). "The phenotype results suggested that USP5 promotes the development and progression of bladder cancer." (PMID 38229092, 2024). "Next, we performed RNA-seq analysis and luciferase pathway screening to explore the mechanism of USP5 in bladder cancer." (PMID 38229092, 2024). "The results suggested that USP5 was obviously highly expressed in bladder cancer compared with normal tissue." (PMID 38229092, 2024). "Our results show that high USP5 expression promotes bladder cancer progression by stabilizing c-Jun and that USP5 is a potential therapeutic target in bladder cancer." (PMID 38229092, 2024). "To clarify the function of USP5 in bladder cancer cells, we examined USP5 expression levels using laboratory-preserved bladder cancer cell lines (UMUC3, T24, EJ)." (PMID 38229092, 2024). "Third, the universality of the stability of USP5 to GPX4 in other bladder cancer subtypes still needs further validation, and future studies could explore biomarkers for combined USP5 and GPX4 therapy." (PMID 40136465, 2025). "Our findings suggest that targeting USP5 could increase ferroptosis and suppress tumor growth in bladder cancer." (PMID 40136465, 2025). "USP5 has been proven to play an important role in the proliferation of bladder cancer (BC)." (PMID 40136465, 2025). "The relationship between USP5 and ferroptosis could be a potential therapeutic target for bladder cancer." (PMID 40136465, 2025). "In addition, USP5 stabilizes Twist1 through its deubiquitinase activity, activating the epithelial–mesenchymal transition pathway in bladder cancer." (PMID 40750708, 2025). "In vitro, USP5 overexpression promotes the proliferation and migration of EJ bladder cancer cells." (PMID 38229092, 2024). "To explore USP5 function in bladder cancer, we constructed USP5-knockout cell lines in T24 cells." (PMID 38229092, 2024). "Altogether, these results indicate that USP5 potentially promotes bladder cancer growth in vivo." (PMID 38229092, 2024). "Xenograft mouse model was used to study the role of USP5 in bladder cancer." (PMID 38229092, 2024). "All the results showed that USP5 is closely related to bladder cancer." (PMID 38229092, 2024). "Our experimental results showed that USP5 is associated with poor prognosis in bladder cancer, Further studies need to be performed to evaluate whether this treatment strategy works against bladder cancer development and progression through specific inhibitors selectively targeting USP5." (PMID 38229092, 2024). "However, the mechanism of USP5 in bladder cancer needs to be determined." (PMID 38229092, 2024). "However, there was few findings suggest that USP5 could be a potential target for bladder cancer therapy." (PMID 38229092, 2024). "However, the role of USP5 in bladder cancer need to be explored." (PMID 38229092, 2024). "Finally, an in vivo xenograft mouse model was used to study the role of USP5 in bladder cancer." (PMID 38229092, 2024). "Finally, we revealed a novel mechanism of USP5 in bladder cancer development and progression." (PMID 38229092, 2024). "For instance, USP5 stabilizes Twist1 through deubiquitination, thereby activating EMT in bladder cancer." (PMID 41208892, 2025).
bladder cancer (continued). "Further studies showed that USP5 interacts with GPX4 and stabilizes GPX4 by inhibiting its ubiquitination These findings revealed USP5 inhibits ferroptosis in bladder cancer cells by stabilizing GPX4." (PMID 40136465, 2025). "Considering that GPX4 is a key factor in the ferroptosis signaling pathway, we analyzed the correlation between USP5 and GPX4 in bladder cancer via the FerrDb database." (PMID 40136465, 2025). "Collectively, our findings reveal a novel mechanism by which USP5 regulates ferroptosis through GPX4 stabilization, highlighting its critical role in bladder cancer development and progression." (PMID 40136465, 2025). "USP5 plays an oncogenic role through deubiquitination of c-Jun, which is an important downstream target of the JNK pathway in bladder cancer." (PMID 38229092, 2024). "First, we analysed the expression of USP5 in bladder cancer in the online GEPIA database, and the results suggested that USP5 is upregulated in bladder cancer patients." (PMID 38229092, 2024). "Inhibitors of USP5 or its downstream targets, such as GPX4, could be developed as novel therapeutic agents for bladder cancer." (PMID 40136465, 2025). "First, we analyzed the correlation between USP5 and GPX4 in bladder cancer." (PMID 40136465, 2025). "Although we genetically silenced USP24 to prove the stabilization of GSDMB by USP24, we could not rule out that USP9x or USP5 acted as deubiquitinases of GSDMB in bladder cancer." (PMID 34326684, 2021).
gastric cancer (5 papers, 2020 to 2025). A primary or metastatic malignant neoplasm involving the stomach. "In gastric cancer (GC) cells, circHECTD1 regulates glutaminolysis via the miR-1256/USP5 axis, activating the β-catenin/c-Myc pathway and promoting tumor progression." (PMID 40917745, 2025). "Furthermore, we evaluated USP5 expression in two paired gastric cancer tissue samples using western blotting, which confirmed that USP5 protein levels were markedly higher in tumor tissues than in normal ones." (PMID 40066708, 2025). "Moreover, in circHECTD1-ablated gastric cancer cells with ectopic overexpression of USP5, the restoration of glutamine, glutamate and α-kG levels occurred, demonstrating the important role of USP5 in the regulation of glutaminolysis." (PMID 32326003, 2020).
glioma (4 papers, 2019 to 2025). A benign or malignant brain and spinal cord tumor that arises from glial cells (astrocytes, oligodendrocytes, ependymal cells). "PTBP1 has been described as one of the key RBPs in regulating AS in neural development and known oncogenic AS gene isoforms such as PKM and USP5 in glioma." (PMID 38662454, 2024).
liver cancer (4 papers, 2020 to 2025). An epithelial or non-epithelial malignant neoplasm that arises from the liver. "Previous studies have shown that USP5 can target LSH to resist ferroptosis in liver cancer cells and promote the malignant transformation of tumors." (PMID 41213937, 2025). "In general, we identify USP5 as a DUB of LSH that suppresses the ferroptosis of liver cancer cells to promote cell proliferation and tumor growth through stabilizing LSH protein." (PMID 37492786, 2023). "In summary, we demonstrated that USP5 promoted liver cancer cells proliferation dependent on stabilizing LSH." (PMID 37492786, 2023). "In contrast, in liver cancer, USP5 stabilizes SLC7A11 through deubiquitination." (PMID 41213937, 2025). "To further investigate the relationship between USP5 and LSH, we first examined the levels of protein expression of USP5 and LSH in normal liver L‐02 cells and several liver cancer cells, and the results showed that USP5 was significantly expressed and positively correlated with LSH in HCC cells." (PMID 37492786, 2023). "Furthermore, the USP5‐mediated deubiquitination of LSH facilitates the tumorigenesis of HCC by upregulating solute carrier family 7 member 11 (SLC7A11) to suppress ferroptosis of liver cancer cells." (PMID 37492786, 2023). "Together, our findings show that USP5 interacts with LSH directly and enhances LSH protein stability through deubiquitination, which, in turn, promotes the development of HCC by suppressing ferroptosis of liver cancer cells, suggesting that USP5 may be a potential therapeutic target for HCC." (PMID 37492786, 2023).
rheumatoid arthritis (4 papers, 2020 to 2025). A chronic, systemic autoimmune disorder characterized by inflammation in the synovial membranes and articular surfaces. "USP5 was reported to be related with proinflammatory function in RA-FLS (rheumatoid arthritis-fibroblast-like synoviocytes." (PMID 37359559, 2023). "USP5 can also stabilize TRAF6 by deubiquitination, but contrary to the results of USP3, overexpression of USP5 increases the activation of NF-κB pathway, promotes the release of NF-κB, and then up-regulates the secretion of pro-inflammatory cytokines such as IL-1β in rheumatoid arthritis (RA)." (PMID 40226783, 2024).
colon cancer (3 papers, 2021 to 2025). "USP5-mediated deubiquitination of ORP8 indirectly aggravates ER stress in colon cancer cells and induces apoptosis." (PMID 37874827, 2023).
diabetic neuropathy (3 papers, 2015 to 2024). A chronic, pathological complication associated with diabetes mellitus, where nerve damages are incurred due to diabetic microvascular injury involving small blood vessels that supply these nerves, resulting in peripheral and/or autonomic nerve dysfunction. "A small organic molecule called suramin greatly decreased diabetic neuropathy in ob/ob mice by causing the dissociation of Cav3.2 from USP5, indicating that USP5 promotes hyperalgesia." (PMID 36834633, 2023). "Disrupting the interaction between Cav3.2 and USP5 using the TAT-cUBP1-USP5 peptide has been shown to reduce the levels of the Cav3.2 calcium channel in vitro, which attenuates thermal hyperalgesia in diabetic neuropathy animals." (PMID 38322269, 2024). "USP5, 7, and 10 are involved in the pathogenesis of diabetic neuropathy, cardiomyopathy, and foot ulcers, respectively." (PMID 36834633, 2023). "Suramin and Cav3.2/USP5 Tat-disruptor peptides were also tested in models of diabetic neuropathy and visceral pain, and provided remarkable protection." (PMID 25889575, 2015).